CPE (carboxypeptidase E)
Diseases named in the same sentence as CPE in open-access papers (continued):
Sharing a sentence is not in itself a finding about the gene and the disease.
endocrine disorders (2 papers, 2017 to 2020). "Accordingly, the T to C mutation of the CPE gene identified in our study which compromises the enzymatic activity of CPE in the AGI_ASP population would likely cause endocrine disorders." (PMID 28114332, 2017).
gastrointestinal disease (2 papers, 2022 to 2023). A disease that occurs in the gastrointestinal system, excluding the hepatobiliary system. "Taken together, this work demonstrates the development and mechanism of claudin/cCpE-binding sFabs that provide a framework and strategy for obstructing claudin/CpE assembly to treat CpE-linked gastrointestinal diseases." (PMID 35952760, 2022). "The insights provided here can be applied to target dimer interfaces with therapeutic molecules that trap or inhibit nascent CpE oligomerization as a means to prevent the building of cytotoxic β-pores, which ultimately could lead to treatments for gastrointestinal diseases induced by CpE." (PMID 37999500, 2023).
adenocarcinoma (1 paper, 2019). A common cancer characterized by the presence of malignant glandular cells. "According to the association analysis for EGFR mutation in patients with adenocarcinoma (n = 108, EGFR mutant = 64), we found 159 suggestive DMPs and six significant DMPs (cg09245319, cg17183999 [USP7], cg06366994 [CPE], cg24992236 [MEG9], cg22144719, and cg22448179 [EGFR])." (PMID 31450665, 2019).
neurological disorders (1 paper, 2017). "The hypothesis that CPE mutation would contribute to neurological disorders is also supported by the animal studies showing that CPE-KO mice had the neuronal loss of the CA3 region of hippocampus, displayed memory deficits and depressive-like behaviors." (PMID 28114332, 2017). "Taken together, we have identified a novel SNP in the CPE gene which results in the loss of its neuroprotective function in cells and may confer neurological disorders in humans." (PMID 28114332, 2017).
CPE also shares sentences with these, for which no sentence is quoted: glioblastoma (4 papers); colorectal cancer (3); ovarian carcinoma (3); embryonal carcinoma (2); influenza (2); insulinoma (2); morbid obesity (2); neutropenia (2); prostate carcinoma (2); autism (1); Autoimmunity (1); brain diseases (1); colon cancer (1); dementia (1); gas gangrene (1); gastroenteritis (1); Hyperglycemia (1); hypogonadism (1); infection (1); leukopenia (1); metastatic tumors (1); neurotoxicity (1); opioid use disorder (1); Pancytopenia (1); peritonitis (1); pneumonia (1); schizophrenia (1); Seizure (1); seminoma (1); small intestinal tumor (1).
A further 4 diseases each share a sentence with CPE in 1 paper.